SUB1 (SUB1 regulator of transcription)
Description:
General coactivator that functions cooperatively with TAFs and mediates functional interactions between upstream activators and the general transcriptional machinery. May be involved in stabilizing the multiprotein transcription complex. Binds single-stranded DNA. Also binds, in vitro, non-specifically to double-stranded DNA (ds DNA).
Synonyms: PC4; p15; p14
Tractability: PROTAC: UniProt records ubiquitination sites on it; ubiquitination databases record sites on it; its protein half-life has been measured.
Gene: Protein-coding gene on chromosome 5 (32,531,633 to 32,604,507, forward strand). Ensembl gene ENSG00000113387.
Subcellular location: Nucleus
Subcellular location (Human Protein Atlas): Nucleoli; Nucleoplasm
Gene Ontology:
Molecular function: double-stranded DNA binding; identical protein binding; protein binding; RNA binding; single-stranded DNA binding; transcription coactivator activity; DNA binding; RNA polymerase II cis-regulatory region sequence-specific DNA binding
Biological process: negative regulation of DNA metabolic process; regulation of transcription by RNA polymerase II; RNA polymerase II promoter clearance; positive regulation of transcription initiation by RNA polymerase II; regulation of DNA-templated transcription
Cellular component: extracellular exosome; nucleolus; nucleoplasm; transcription regulator complex; nucleus
Genetic constraint (gnomAD): Loss-of-function variants: 0 observed, 7.6 expected, observed/expected ratio (o/e) 0, 90% interval 0 to 0.39. That is too few expected variants to judge how well the gene tolerates losing a copy. Missense variants: 39 observed, 91.51 expected, observed/expected ratio (o/e) 0.43, 90% interval 0.33 to 0.56. Synonymous variants: 29 observed, 28.81 expected, observed/expected ratio (o/e) 1.01, 90% interval 0.75 to 1.37.
Homologues: Orthologues: guinea pig SUB1 (100% identical), macaque SUB1 (100% identical), pig SUB1 (100% identical), dog SUB1 (98% identical), rabbit SUB1 (97% identical), mouse Sub1 (94% identical), rat Sub1 (92% identical), tropical clawed frog sub1 (82% identical), zebrafish sub1a (80% identical), rat LOC103693281 (73% identical), zebrafish sub1b (70% identical), Caenorhabditis elegans T13F2.2 (35% identical).
Diseases named in the same sentence as SUB1 in open-access papers:
SUB1 is named in the same sentence as 25 diseases in open-access papers, as found by Europe PMC text mining. Sharing a sentence is not in itself a finding about the gene and the disease. The quoted sentences say what the papers report.
malaria (10 papers, 2012 to 2025). Malaria is a serious and sometimes fatal disease caused by a parasite that commonly infects a certain type of mosquito which feeds on humans. "Therefore, the authors highlight the feasibility of developing broad-spectrum drugs capable of inhibiting the SUB1 enzyme of the three main species that cause malaria in humans." (PMID 41011189, 2025). "Plasmodium falciparum subtilisin-like protease 1 (SUB1) is a key regulator of parasite egress during the asexual blood stage of malaria." (PMID 41011189, 2025). "Malaria parasite egress from host erythrocytes (RBCs) is regulated by discharge of a parasite serine protease called SUB1 into the parasitophorous vacuole (PV)." (PMID 33932049, 2021). "Here we identify a stand-alone subtilisin propeptide-like protein that is probably expressed in the PV of asexual blood stages of the malaria parasite and that is a potent and selective inhibitor of SUB1." (PMID 31942933, 2020). "SUB1 is already considered a promising drug target for malaria chemotherapy, being essential in both hepatic and asexual blood stages of the Plasmodium life cycle." (PMID 30941868, 2019). "Towards this ambitious aim, we decided to dissect the similarities between the SUB1 orthologues from all three major human malaria pathogens in order to ascertain the likelihood of developing a single inhibitor for all three enzymes." (PMID 26826801, 2016). "Our findings demonstrate that it should be possible to develop ‘pan-reactive’ drug-like compounds that inhibit SUB1 in all three major human malaria pathogens, enabling production of broad-spectrum antimalarial drugs targeting SUB1." (PMID 22543039, 2012). "Our evidence that the human malaria pathogen SUB1 orthologues share very similar active site structures led us to explore the potential for producing inhibitors with the capacity to inhibit all three proteases." (PMID 22543039, 2012). "► Molecular modelling of subtilisin-like protease 1 (SUB1) of three human malaria pathogens shows similarity in active site." (PMID 22543039, 2012). "SUB1 is a subtilisin-like serine protease that is critical during malaria parasite egress." (PMID 34884766, 2021). "On the basis of the rational approach described here, we have predicted and experimentally demonstrated that inhibitors 1 and 2 are able to potently inhibit SUB1 enzymes of the most important human malaria pathogens, confirming that the development of pan-SUB1 inhibitors is a feasible task." (PMID 26826801, 2016). "Our results show that inhibitors of SUB1 could be used in prophylactic approaches to control or block the pre-erythrocytic stage of the malaria parasite life cycle." (PMID 24348254, 2013). "Our results enhance our understanding of malarial liver stage biology, provide new tools for studying essential gene function in malaria, and suggest that inhibitors of SUB1 could be used as prophylactic drugs to prevent clinical malaria." (PMID 24348254, 2013). "However, mass spectrometric analysis of blood-stage schizonts of the human malaria pathogen P. falciparum has detected only between 1 and 8 peptides, suggesting that – as with many enzymes - SUB1 is likely a poorly abundant constituent of the total proteome." (PMID 24348254, 2013). "Our results indicate that inhibitors of SUB1 could be used in prophylactic approaches to control or block the clinically silent pre-erythrocytic stage of the malaria parasite life cycle." (PMID 24348254, 2013). "Finally, we used the recombinant enzymes to validate some major predictions from our modelling work, and to present a proof-of-principle that substrate-based inhibitors can be developed that target SUB1 orthologues from all three major human malaria pathogens." (PMID 22543039, 2012). "All Plasmodium species, including the most important human malaria pathogens Plasmodium falciparum, Plasmodium vivax, and Plasmodium knowlesi, possess a single ortholog of SUB1 with similar (though not identical) substrate specificity." (PMID 33975947, 2021).
malaria (continued). "A previous transcriptomic and proteomic analysis of the rodent malaria species P. yoelii indicated the presence of P. yoelii sub1 mRNA in liver stages but detected no SUB1 protein by mass spectrometry." (PMID 24348254, 2013). "As a result, inhibitors of PfSUB1 are unlikely to show similar potency against SUB1 orthologs from rodent malaria parasite species such as Plasmodium berghei, making these parasite species unsuitable as model systems for assessing the in vivo efficacy of our compounds." (PMID 33975947, 2021).
breast carcinoma (4 papers, 2017 to 2025). "Upon inquiring for potential genes contributing to cisplatin resistance due to MECOM amplification, we identified transcription co-activator SUB1, a proposed carcinogenic gene implicated in hepatoblastoma malignancy and associated with poor prognosis in breast cancer metastasis." (PMID 40664642, 2025). "The SUB1 gene can promote breast cancer proliferation and metastasis through the c-Myc-mediated Warburg effect." (PMID 34512726, 2021). "One gene targeted by hsa-miR-584-5p – FOXA1 – and two genes targeted by hsa-miR-570-3p – ABL2 and SUB1 – have been described in previous breast cancer studies." (PMID 34512726, 2021). "Among the candidates unique to our study are several proteins described to be involved in different cancer types in humans: for example, NOLC1 in multidrug resistant non-small cell lung cancer (the same cancer MALAT1 has originally been identified), DEK in breast cancer and SUB1 in prostate cancer." (PMID 32050583, 2020).
prostate carcinoma (2 papers, 2016 to 2020). A carcinoma that arises from epithelial cells of the prostate gland. "Thus, our study suggests that miR-101 loss results in increased SUB1 expression and subsequent activation of known oncogenes driving prostate cancer progression and metastasis." (PMID 27270442, 2016). "Through gene knockdown studies, we demonstrate that SUB1 has an important role in prostate cancer cell proliferation and invasion both in vitro and in vivo." (PMID 27270442, 2016). "Taken together, these observations demonstrate the involvement of SUB1 in the proliferation, migration, invasion and colony formation of prostate cancer cells in vitro." (PMID 27270442, 2016). "Next, we tested cell motility after stable SUB1 knockdown in prostate cancer cells using wound healing assay." (PMID 27270442, 2016). "To determine the functional significance of SUB1 expression in prostate cancer, we perturbed SUB1 levels in prostate cells and investigated the effect of this modulation on cell proliferation, migration and invasion." (PMID 27270442, 2016). "Knockdown of SUB1 in prostate cancer cells resulted in reduced cell proliferation, invasion and migration in vitro, and tumor growth and metastasis in vivo." (PMID 27270442, 2016). "To find the effect on SUB1 protein levels, we treated prostate cancer cells with precursor miRs, miR-101, -23a, -23b, -30a, -30b, -124 and -122 individually and measured SUB1 protein levels." (PMID 27270442, 2016). "This study therefore demonstrates functional role of SUB1 in prostate cancer, and identifies its regulation and potential downstream therapeutic targets of SUB1 in prostate cancer." (PMID 27270442, 2016). "In this study, we show that miR-101 regulates SUB1 expression and SUB1 has a role in prostate cancer growth." (PMID 27270442, 2016). "To validate this observation, we performed qPCR using RNA from multiple prostate cancer and benign tissues and confirmed increased expression of SUB1 in metastatic prostate cancer tissues relative to benign prostate samples." (PMID 27270442, 2016). "Our investigations also demonstrate the role of SUB1 in prostate cancer cell proliferation and invasion." (PMID 27270442, 2016). "To evaluate SUB1-mediated effects in prostate cancer progression, we performed gene expression analysis using RNA from SUB1 knockdown prostate cell lines." (PMID 27270442, 2016). "We used both transient RNA interference and stable knockdown strategies targeting SUB1 in aggressive prostate cancer cell lines DU145 and PC3 and hormone-responsive LnCaP and VCaP cells." (PMID 27270442, 2016). "This study shows SUB1 overexpression in aggressive prostate cancer and reveals therapeutic options to block SUB1-mediated oncogenesis." (PMID 27270442, 2016). "The present study shows an increased expression of SUB1 in prostate cancer." (PMID 27270442, 2016). "Furthermore, we investigated the potential role of SUB1-induced PLK1 in prostate cancer invasion by using PLK1-specific siRNA pool or inhibitor volasertib." (PMID 27270442, 2016). "Here, we show increased SUB1 expression in prostate cancer cell lines and tissues." (PMID 27270442, 2016). "In this study, we characterized SUB1 expression specifically in aggressive prostate cancer." (PMID 27270442, 2016). "Thus, these consolidated observations underscore a downstream role for PLK1, C-MYC and CDKN1B in SUB1-mediated prostate cancer cell proliferation and invasion." (PMID 27270442, 2016). "Similarly, elevated levels of SUB1 protein was observed in metastatic prostate cancer cell lines relative to benign cell lines." (PMID 27270442, 2016). "In this study, we show elevated expression of SUB1 in aggressive prostate cancer." (PMID 27270442, 2016). "Additionally, we validated both PLK1 mRNA and protein levels across benign, prostrate carcinoma and metastatic prostate cancer tissues by qPCR and immunoblot analysis, respectively, which confirmed the direct correlation between SUB1 and PLK1." (PMID 27270442, 2016).
prostate carcinoma (continued). "Additionally, we investigated SUB1 protein expression in a large number of prostate cancer samples by immunohistochemical analysis, which showed weak or no reactivity in many benign tissues but stronger staining in aggressive prostate cancer tissue and metastatic prostate tumors." (PMID 27270442, 2016). "Furthermore, SUB1 overexpression elevated PLK1 and C-MYC expression, and reduced CDKN1B expression, showing SUB1 dysregulation triggers alterations in critical oncogenes and tumor suppressors in prostate cancer." (PMID 27270442, 2016). "Additionally, SUB1 and PLK1 mRNA levels are correlated in prostate cancer cell lines." (PMID 27270442, 2016).
atherosclerosis (1 paper, 2021). A disease characterized by the build-up of fatty material and calcium deposition in the arterial wall resulting in partial or complete occlusion of the arterial lumen. "Considering SUB1’s strong activation status and its more central position in both TLR networks, we chose to pursue further investigation on the role of macrophage SUB1 in atherosclerosis." (PMID 34378353, 2021). "To determine the role of Sub1 in TLR signaling‐induced atherosclerosis, we applied myeloid‐specific Sub1 KO in the chow‐fed ApoE−/− murine model of atherosclerosis." (PMID 34378353, 2021). "As a novel master regulon in atherosclerosis, we further investigated the role of macrophage Sub1 in atherosclerosis." (PMID 34378353, 2021).
COVID-19 (1 paper, 2025). A disease caused by infection with severe acute respiratory syndrome coronavirus 2. "While these sites are highly attractive and have been extensively explored, other potential binding regions, such as SUb1 and the Zn(II) domain, are less explored and may hold untapped potential for future COVID-19 drug discovery and development." (PMID 39942596, 2025).
Cryptosporidium infection (1 paper, 2025). "Drawing parallels from plasmodium research, it was hypothesized that Cryptosporidium SUB1 may play a similar role in egress, making it a potential target for inhibiting Cryptosporidium infection." (PMID 39902829, 2025).
cyst (1 paper, 2025). A sac-like closed membranous structure that may be empty or contain fluid or amorphous material. "Specifically, Sub1-RNAi led to a decrease in follicle formation and an increase in the proportion of cysts, suggesting that Sub1-RNAi impaired cyst breakdown, thereby hindering the formation of primordial follicles." (PMID 40332359, 2025). "The targeted knockdown of Sub1 and Stk31 in vitro resulted in a marked decrease in ovarian germ cell numbers, alongside disruptions in cyst breakdown and follicular assembly." (PMID 40332359, 2025).
female fertility (1 paper, 2021). A fertility quality of inhering in a female by virtue of the bearer's disposition to initiate, sustain, or support reproduction. "NCU04001: (Δτ = +0.87 h) identified as female fertility 7 (ff-7), this zinc-finger TF was found to interact with SUB-1 (NCU01154) in regulating the expression of several genes in LL and DD conditions." (PMID 33792687, 2021).
glioma (1 paper, 2020). A benign or malignant brain and spinal cord tumor that arises from glial cells (astrocytes, oligodendrocytes, ependymal cells). "Recurrent deletions in previously unknown glioma genes NT5C2, ADGRL2, and UIMC1 were observed whilst SUB1, CES1, and ITGA6 were frequently methylated in human LGGs; frequent CNVs in these genes were also present in human GBMs." (PMID 32727536, 2020).
lung carcinoma (1 paper, 2021). "The high expression of CDK8 and SUB1 was correlated with the poor survival of patients with lung cancer." (PMID 34362882, 2021). "The expression of CDK8 and SUB1 was also higher in lung cancer patients with high HIF1α expression, further suggesting the upregulation of CDK8 and SUB1 by hypoxic stress." (PMID 34362882, 2021).
metastatic prostate carcinoma (1 paper, 2016). A carcinoma that arises from the prostate gland and has spread to other anatomic sites. "The expression profiling and transcriptome sequence analysis showed upregulation of SUB1 in metastatic prostate cancer." (PMID 27270442, 2016).
osteosarcoma (1 paper, 2023). A usually aggressive malignant bone-forming mesenchymal neoplasm, predominantly affecting adolescents and young adults. "In osteosarcoma, SMARCAL1, IRS1, SUB1, HMGA2, and FANCM were identified as Supertargets." (PMID 37297004, 2023).
ovarian carcinoma (1 paper, 2025). A malignant neoplasm originating from the surface ovarian epithelium. "An AUC value of 0.58 (p value = 2.8e-03) suggested a potential of SUB1 as a predictive biomarker of clinical utility to predict relapse free survival of ovarian cancer patients in response to platin therapy." (PMID 40664642, 2025). "Considering a better AUC for SUB1, we analysed the prognostic significance of SUB1 (Probe id = 221727_at) using Kaplan Meier survival plot, determining the impact of SUB1 expression on progression-free survival (PFS) of ovarian cancer patients." (PMID 40664642, 2025).
ovarian tumor (1 paper, 2025). "Further, qRT-PCR analysis confirmed that JIB-04 treatment and MECOM siRNA-mediated silencing reduced SUB1 transcript levels in ovarian tumor cells." (PMID 40664642, 2025).
Ventricular hypertrophy (1 paper, 2021). Enlargement of the cardiac ventricular muscle tissue with increase in the width of the wall of the ventricle and loss of elasticity. "As macrophage infiltration into the myocardium can produce ventricular hypertrophy, we investigated any possible effects of macrophage Sub1 KO on the murine myocardium." (PMID 34378353, 2021).